MYH7 (myosin heavy chain 7)
Diseases named in the same sentence as MYH7 in open-access papers (continued):
Sharing a sentence is not in itself a finding about the gene and the disease.
cardiomyopathy (continued). "For the remaining MYH7 HCM samples, variants in the following other cardiomyopathy genes were also found: DSP, MHY6, NEBL, PSEN1, RBM20, and TTN." (PMID 32344918, 2020). "Data on de novo mutations in non-syndromic cardiomyopathies are limited and include variants in ACTC, MYH7, TNNI3, TNNT2, and TPM1." (PMID 32013205, 2020). "In 6 of 10 cases of sporadic DCM and in single cases of RCM and HCM, we found de novo mutations in genes previously associated with cardiomyopathy (CRYAB, DSP, MYH7, SCN5A, TNNC1, and TTN)." (PMID 32013205, 2020). "In 8/12 probands (66.7%), we found likely causative variants in known cardiomyopathy genes (TTN, DSP, SCN5A, TNNC1, TPM1, CRYAB, and MYH7), which were confirmed as de novo (six DCM, one HCM, and one RCM case)." (PMID 32013205, 2020). "In 8 (66.7%), we found de novo variants in known cardiomyopathy genes (TTN, DSP, SCN5A, TNNC1, TPM1, CRYAB, MYH7)." (PMID 32013205, 2020). "Three cases (34, 286 and 290) had one variant in a cardiomyopathy gene and one in a channelopathy gene (CSRP3 and TRPM4, PKP2 and ANK2, MYH7 and KCNH2, respectively)." (PMID 30615648, 2019). "Future work will extend the MYH7 framework to other cardiomyopathy genes, which will likely require only minimal additional specifications." (PMID 29300372, 2018). "Twenty-six pathogenic or likely pathogenic mutations involved in 10 genes, and MYH7(8/26) and MYBPC3 (6/26) mutations accounted for more than 50% of the variants found in cardiomyopathy cases." (PMID 30165862, 2018). "Overall, patient-specific iPSC-CMs from a family with MYH7 E848G–induced systolic dysfunction along with isogenic control subjects recapitulate the contractile dysfunction that is characteristic of this cardiomyopathy." (PMID 30623132, 2018). "The Cardiomyopathy Expert Panel selected MYH7, a key contributor to inherited cardiomyopathies, as a pilot gene to develop a broadly applicable approach." (PMID 29300372, 2018). "Whilst clinical presentation of MYH7 skeletal myopathy is starting to be better clarified, more complexity arises with the concomitant presence of cardiomyopathy." (PMID 27387980, 2016). "Genetic testing, including a targeted cardiomyopathy panel and whole exome sequencing, did not identify any pathogenic variants, including in MYH7 or MYBPC3." (PMID 40546560, 2025). "The review identified key gene variants affecting athletic performance: endurance (AMPD1, PPARGC1A), power (ACTN3, NOS3), strength (PPARG), and injury susceptibility (COL5A1, MMP3), while also examining inherited conditions like cardiomyopathies (MYH7, MYBPC3)." (PMID 40724525, 2025). "While an MYH7 variant was also detected, its clinical relevance was ruled out due to the family's absence of associated cardiomyopathy phenotypes." (PMID 40303613, 2025). "Another patient whose MYH7 variant was initially classified as VUS also had a rare nonsynonymous variant in RNA binding motif protein 20 (RBM20 p.Ile921Val), a titin-splicing gene implicated in cardiomyopathy." (PMID 40791945, 2025). "Furthermore, probands I, II, and III also inherited additional heterozygous cardiomyopathy-associated mutations, including DSP c.7883T>C, SCN5a c.3577C>T, or MYH7 c.427C>T, respectively." (PMID 39253717, 2024). "Cardiomyopathy-related genes such as B-type natriuretic peptide (nppb), encoding the BNP protein, an indicator of heart failure, and myosin heavy chain 7 (Myh7), encoding the beta (slow) heavy chain subunit of cardiac myosin, were both altered in db/db mice compared with WT mice." (PMID 37895057, 2023).
cardiomyopathy (continued). "Genes associated with ER stress (e.g., ATF4, NUPR1, DDIT3, TRIB3, CHAC1, SESN2, HERPUD1) were upregulated and genes related to cardiomyopathy and sarcomeric structure (e.g., MYH7, SYNPO2L, LDB3, ACTN2, MYLK3) were downregulated by afatinib, sorafenib, or high-dose ponatinib." (PMID 37069550, 2023). "Interestingly, protein and mRNA levels of MYH7, MYL3, and ACTC1, the major sarcomere genes whose variants can cause inherited cardiomyopathies such as HCM, and dilated cardiomyopathy were significantly increased in SCH cases." (PMID 37284852, 2023). "We identified novel DNVs in diagnostic-grade genes (RYR2, TNNT2, PTPN11, MYH7, LZR1, NKX2-5), and five cases harbouring a combination of prioritised variants, suggesting that oligogenic inheritance and genetic modifiers contribute to cardiomyopathies." (PMID 36357925, 2022). "In this study, we observed rare P/LP/VUS+ variants in 4 genes associated with cardiomyopathy (MYH7, CRYAB, SCN5A, and MYBPC3) in individuals without a history of MI or HF and with extensive myocardial fibrosis indicated by CMR." (PMID 35265679, 2022). "In particular, MYH7 truncating variants (MYH7tv), generally considered nonpathogenic for cardiomyopathies, were 20-fold enriched in LVNC cases over controls." (PMID 33500567, 2021). "Bulk RNA-seq analysis of endomyocardial biopsy specimens from cardiomyopathy patients showed that gene expression greatly depended on the pathogenic variant involved, including TTNtv, the LMNA variant, the RBM20 variant, and the MYH7 variant." (PMID 34830403, 2021). "In the sarcomeric group, 3 patients had a variant of unknown significance (2 MYH7 and 1 TNNI3); therefore, the cardiomyopathy in these patients might have been affected by other variables that we have currently not yet identified." (PMID 33605084, 2021). "In addition, a cluster of antisense lncRNAs in the MYH7 locus was noticed to be essential in early development of cardiomyopathy under pressure-overload." (PMID 32429430, 2020). "Besides the hub genes of MYBPC3, MYH7, and DSP, these subnetworks also include several genes that have been implicated in cardiomyopathy, such as TPM1, ACTC1, DES, TCAP, JUP, and DSG2." (PMID 32344918, 2020). "While HCM has been attributed to monogenic perturbations in sarcomeric genes, like MYBPC3 and MYH7, there is often dramatic phenotypic variability, even within a single family, with some family members having other cardiomyopathy subtypes, including DCM and ARVC, or hybrid phenotypes." (PMID 32344918, 2020). "MYH7 mutations have also been reported in other cardiomyopathies such as non-compaction cardiomyopathy and restrictive cardiomyopathy." (PMID 30650640, 2019). "Overall, we report a unique cardiomyopathy due to MYH7 E848G mutation that clinically does not clearly fit a diagnosis of HCM or DCM." (PMID 30623132, 2018). "Additionally, BPD‐treated ABCB8 KO mice demonstrated attenuated expression of Nppa, Nppb, and Myh7, which are upregulated in cardiomyopathy." (PMID 26896449, 2016). "Initial testing of these MYH7-cardiomyopathy specific rules shows a high level of concordance." (PMID 27324065, 2016). "Notably, despite being the predominant myosin isoform expressed in the heart, not all MSM-causing MYH7 mutations engender human cardiomyopathy." (PMID 39485824, 2025). "Although these RYR2 and MYH7 variants are classified as VUS, based on their association with cardiomyopathies and evidence of high pathogenic scores, we suggest that these variants may negatively impact cardiac output during vigorous exercise and might contribute to the development of EHI." (PMID 39457051, 2024). "Moreover, when we analyzed the ratio of Myh7 / Myh6 expression, a common ratio investigated in cardiomyopathy readouts, we observed between 15 and 20 fold differences in diabetes, which was significant in WT mice and trending in KO animals (WT: p < 0.05, KO: p = 0.1)." (PMID 38054572, 2023).
cardiomyopathy (continued). "In some but not all patients with cardiomyopathy due to MYH7 mutations, but without overt muscle weakness, cores may be identified in skeletal muscle fibers." (PMID 22918376, 2013). "Notably, sarcomeric genes such as TNNI3, TNNT2, MYBPC3, and MYH7 are classically associated with HCM, but the findings obtained by the present review demonstrate their significant role in DCM as well, establishing them as shared genetic substrates between the two cardiomyopathies." (PMID 41374444, 2025). "Myh7 is both highlyexpressed and involved in multiple processes in KEGG enrichment, including avariety of cardiomyopathy, myocardial contraction, and adrenergic signaling incardiomyocytes." (PMID 39077026, 2023). "Furthermore, several mutations in MYH7 have been associated with congenital heart defects (CHDs), including Ebstein’s anomaly, bicuspid aortic valve (BAV), and ventricular septal defect (VSD), but thus far always in combination with cardiomyopathy (typically NCCM)." (PMID 28864942, 2017). "Although numerous studies have consistently reported this isoform switch in various cardiomyopathies—including DCM, hypertrophic cardiomyopathy (HCM), ischaemic cardiomyopathy (ICM), and aortic stenosis—comparative data on MYH6/MYH7 expression ratios in healthy human LVs remain limited." (PMID 41295372, 2025). "In contrast, cardiomyopathies like HCM arise from sarcomere mutations (e.g., Myosin Heavy Chain 7 (MYH7)) independent of lifestyle factors." (PMID 40662044, 2025). "Discordant interpretations exist for 229 variations in Hypertrophic Cardiomyopathy, with the majority of these variations located in well-known cardiomyopathy-related genes such as MYBPC3 (68 variations), MYH7 (49 variations), TNNI3 (20 variations), or TNNT2 (20 variations)." (PMID 37946154, 2023). "Two PV/LPVs related to cardiomyopathy were detected in the TTN and MYH7 genes." (PMID 36005429, 2022). "The correlation of features between these models suggest the use of our KO zebrafish as a platform to investigate the molecular mechanisms of MYH7-related disorder such as non-compaction cardiomyopathies." (PMID 35463789, 2022). "By performing MCL clustering, we highlighted four subnetworks that could play significant roles in HCM, including one mtDNA-subnetwork and three cardiomyopathy-gene-centered networks: MYBPC3-, MYH7-, and DSP-subnetworks." (PMID 32344918, 2020). "Given the overall limited numbers of myosin DCM PV and LPVs, we also assessed two previously reported DCM MYH7 PVs, S532P and F764L that were not identified in the cardiomyopathy cohort studied here." (PMID 28606303, 2017). "Using muscle biopsy specimens obtained from patients, molecular analysis of 10 distinct MYH7 mutations in the light-meromyosin (LMM) core of the thick filament, which result in skeletal muscle diseases rather than cardiomyopathies, found a significant decrease in the proportion of SRX myosin." (PMID 39192034, 2024). "Missense, rather than truncating, variants in MYH7 and truncating, rather than missense, variants in MYBPC3 are well-documented to be the mutational classifications associated with HCM, instead of other cardiomyopathy subtypes." (PMID 32344918, 2020).
hypertrophic cardiomyopathy (130 papers, 2007 to 2026). "Pathogenic variants in myosin heavy chain 7 (MYH7) cause hypertrophic cardiomyopathy (HCM) or dilated cardiomyopathy (DCM)." (PMID 41289020, 2026). "The diagnosis was confirmed by endomyocardial biopsy-consistent with hypertrophic cardiomyopathy-and genetic testing, which identified a pathogenic MYH7 variant (c.4145G>A, p.R1382Q)." (PMID 41788559, 2026). "MYH7, encoding β‐myosin heavy chain, is one of the most common genes involved in hypertrophic cardiomyopathy." (PMID 39981966, 2025). "Variation of MYH7 can cause hypertrophic cardiomyopathy (HCM), and MYH7 has also been considered the hub gene in oral cancer." (PMID 40709170, 2025). "One individual was a carrier (1/280) of the missense c.2609G>T p.(Arg870Leu) variant in the MYH7 gene, which has been reported as a P variant for hypertrophic cardiomyopathy." (PMID 40699671, 2025). "In some of these diseases (for example, sickle cell disease, Marfan syndrome, and hypertrophic cardiomyopathy caused by mutations in MYH7), it has been reported that missense mutations have more detrimental effects than nonsense mutations." (PMID 39939773, 2025). "Due to the importance of the β-MHC isoform, pathogenic variants of the MYH7 gene are a major contributor to hypertrophic cardiomyopathy and are often clustered in the converter domain, a critical region for mechanical force transduction." (PMID 40004541, 2025). "MYH6 and MYH7, which encode cardiac myosin heavy chains and are frequently mutated in hypertrophic cardiomyopathy (HCM), were edited in 10% of studies to correct sarcomeric dysfunction." (PMID 40465697, 2025). "Applying this approach to a sarcomeric mutation associated with hypertrophic cardiomyopathy, we show that R403Q/MYH7-mutated minipigs exhibit a higher ON fraction compared to controls." (PMID 40463011, 2025). "Genes that show increased expression at W8 relative to later time points include MYH7, a protein found in muscle fibers and is associated with hypertrophic cardiomyopathy." (PMID 40569389, 2025). "A low prevalence of MYH7/MYBPC3 mutations amongFamilial Hypertrophic Cardiomyopathy patients in India." (PMID 40556978, 2025). "This was evidenced by the observed increase in the cross‐sectional area by WGA staining and the significant increase in the MYH7 gene, which was specifically associated with hypertrophic cardiomyopathy." (PMID 39054575, 2024). "For instance, one of the causal mutations located in the coding region of myosin heavy chain 7 (MYH7) gene linked to hypertrophic cardiomyopathy has been demonstrated to modify the secondary structure of the MYH7 mRNA." (PMID 38867209, 2024). "Variants in β‐cardiac myosin (MYH7) and other regulators of contractility are associated with hypertrophic cardiomyopathies (HCM) and dilated cardiomyopathies (DCM)." (PMID 39558513, 2024). "Two variants, p.Glu949Val and p.Asp1339Gly, were identified in MYH7, one of the major genes for hypertrophic cardiomyopathy (HCM)." (PMID 39457051, 2024). "A dominant missense mutation in the MHC gene, MYH7, was first identified many years ago to cause hypertrophic cardiomyopathy." (PMID 37788100, 2023). "We fertilized WT oocytes with sperm donated by a subject carrying a heterozygous mutation in exon 22 of MYH7 gene (1 bp C > T substitution; g.15819 C > T, NG_007884.1) located on chromosome 14, and implicated in familial hypertrophic cardiomyopathy (HCM)." (PMID 36882397, 2023). "MYH7 mutations can cause skeletal muscle diseases, including myosin deposition myopathy, and Distal Laing myopathy is also closely related to hypertrophic cardiomyopathy." (PMID 37340028, 2023). "In total, 53 individuals carried the MYH7 p.(Arg1712Gln) variant, of whom 38 (72%) were diagnosed with hypertrophic cardiomyopathy (HCM)." (PMID 37488328, 2023).
hypertrophic cardiomyopathy (continued). "To clarify any differences in APs between mouse and man, we performed additional experiments and assessed the AP characteristics of hiPSC-CMs from a hypertrophic cardiomyopathy patient carrying R403Q MYH7 mutation (MYH7 403/+, see family pedigree)." (PMID 37438479, 2023). "Mice expressing the R403Q mutation in MYH6, encode the predominant myosin isoform in the adult mouse heart that is highly homologous in sequence with MYH7, develop hallmark features of hypertrophic cardiomyopathy from 30 weeks of age5." (PMID 37438479, 2023). "This phenomenon, recently described as a stochastic allelic expression in DCM, has been reported in hypertrophic cardiomyopathy patients with variants in myosin heavy chain 7 (MYH7) and myosin-binding protein C3 (MYBPC3)." (PMID 37723491, 2023). "We report a case of acute MR in a heart transplant patient with a mutation in the MYH7 gene encoding the protein β-myosin heavy chain, resulting in familial hypertrophic cardiomyopathy." (PMID 37744343, 2023). "KCNH2‐T474I and KCNQ1‐Q530* mutations induce long QT syndrome, while MYBPC3‐Q401*, MYBPC3‐Q1259*, MYH7‐R403W, and MYH7‐R719W mutations induce hypertrophic cardiomyopathy." (PMID 34874112, 2022). "The mutations of MYH7 have been demonstrated in approximately 25% of patients with the overlap of hypertrophic cardiomyopathy and LQTs." (PMID 36303204, 2022). "Multiple reports have shown the pathological symptoms of c.2167C > G (R723G) and c.2167C > T (R723C) mutations in MYH7 gene locus leading to hypertrophic cardiomyopathy in human patients." (PMID 35784482, 2022). "We report three novel protein truncating variants in APOB and one in MYH7 observed in individuals with hypobetalipoproteinemia and hypertrophic cardiomyopathy, respectively." (PMID 34691145, 2021). "MYH7 variants are associated with familial hypertrophic cardiomyopathy (CMH1 [MIM: 192600]) and dilated cardiomyopathy (CMD1S [MIM: 613426])." (PMID 33300982, 2021). "The ventricular/slow myosin heavy chain isoform (Myh7), a gene associated with increased fibrosis and hypertrophic cardiomyopathy, showed a trend to increase in the BACHD, with no significant changes in the BMYO in comparison to the WT." (PMID 35004919, 2021). "Myosin heavy chain 7 (MYH7) is a major causative gene for hypertrophic cardiomyopathy, but the affected signaling pathways and therapeutics remain elusive." (PMID 34935644, 2021). "A previous report confirmed that many pathogenic variants of hypertrophic cardiomyopathy are found in genes encoding sarcomere proteins, of which the gene encoding cardiac β-myosin heavy chain (MYH7) is a hotspot gene with pathogenic mutations." (PMID 34330286, 2021). "Remarkably, the location of variants in MYH7 in LVNC was different from that in hypertrophic cardiomyopathy (HCM) patients." (PMID 32183154, 2020). "The first knock-in mouse model of hypertrophic cardiomyopathy introduced the c.1208G>A p.(Arg403Gln) variant into the endogenous murine Myh7." (PMID 31783775, 2019). "The point mutation R723G (c.2223C > G, NM_000257) in the ß-MyHC gene MYH7 causes severe hypertrophic cardiomyopathy in human patients." (PMID 29555974, 2018). "In four cases the result engendered a reversal to a standard decision from an adverse decision previously made on the basis of family history: Bra/Ov cancer (n = 2), colorectal cancer (n = 1), and MYH7 gene associated with hypertrophic cardiomyopathy (n = 1)." (PMID 29891881, 2018). "In conclusion, we reported that MYBPC3 is the most commonly mutated gene among our study population with hypertrophic cardiomyopathy, almost twice that of MYH7, which was previously suggested as the most common genetic cause of familial HCM." (PMID 29121657, 2017). "The MYH7 gene has long been understood to be a cause of Hypertrophic Cardiomyopathy (HCM), a relationship which is clearly illustrated by the well-known, pathogenic p.Arg403Gln variant." (PMID 27446933, 2016).